OGT (O-linked N-acetylglucosamine (GlcNAc) transferase)
Diseases named in the same sentence as OGT in open-access papers (continued):
Sharing a sentence is not in itself a finding about the gene and the disease.
colon cancer (continued). "In colon cancer, both O-GlcNAc and OGT abundance increased in clinical patient samples." (PMID 37086786, 2023). "(2021) demonstrate that a combination of TRAIL and OSMI-1 (OGT inhibitor) enhances TRAIL-induced apoptosis in colon cancer cells and xenograft tumors by lowering the activity of Inhibitory κB Kinase β (IKKβ) and inhibition of downstream NF-κB pro-survival signaling." (PMID 36059648, 2022). "Moreover, we and others observed increased contents of O-GlcNAcylation and OGT in human colon cancer samples in comparison with normal tissues." (PMID 33126652, 2020). "Thus, a further research about the mutual regulatory mechanism between XIAP and OGT is needed to understand the pathogenesis of colon cancer and consider the potential therapeutic interest for colon cancer." (PMID 32994395, 2020). "Moreover, O-GlcNAcylation of XIAP suppresses colon cancer cell growth and invasion by promoting the proteasomal degradation of OGT." (PMID 32994395, 2020). "Taken together, these results show that XIAP is an E3 ubiquitin ligase of OGT, is modified by O-GlcNAc at serine 406, and this modification on XIAP leads to the polyubiquitination and degradation of OGT, resulting in the inhibition of colon cancer cell growth and invasion." (PMID 32994395, 2020). "We found that the inhibition of OGT in both primary and metastatic colon cancer cell lines induced not only an increase in stem cell markers expression but also, induced an aggressive phenotype associated with the appearance of double positive stem cell markers subpopulations." (PMID 31139149, 2019). "Increased O-GlcNAcylation in colon cancer cells, either by OGT overexpression or OGA inhibition, reduces phosphorylation of AMPK at Thr172, activates mTOR and induces cell growth in vitro in LoVo cell line and in vivo in LoVo cell-derived tumors of BALB/c-nu/nu mice." (PMID 30356686, 2018). "Similarly in lung and colon tumor tissues, OGT expression was elevated compared with surrounding normal tissue." (PMID 27703839, 2016). "For example, the increased levels of OGT/O-GlcNAcylation in patients with lung cancer or colon cancer are closely correlated with poor overall survival, as well as the anchorage-independent growth, migration, and invasion ability of lung and colon cancer cell lines." (PMID 33194731, 2020). "However, colon cancer cells express higher amounts of OGT and O-GlcNAcylation than normal cells." (PMID 27252680, 2016). "Our previous interactome study showed an interaction between XRCC4 and OGT, implying that XRCC4 undergoes O-GlcNAc modifications in HCT116 colon cancer cells." (PMID 41513635, 2026). "Increased protein O‐GlcNAc modification and changes in the level of OGT or OGA expression are commonly observed features of many types of cancer, including leukemia, breast, prostate, and colon cancers." (PMID 35347892, 2022). "We examined the proteins that regulate OGT in HCT116 cells because previous research has shown that silencing OGT significantly reduces cell proliferation and migration in human colon cancer cells." (PMID 32994395, 2020). "We have also demonstrated that inhibition of mTOR affects OGT protein level and overall O-GlcNAcylation levels in HCT116 colon cancer cell line." (PMID 30356686, 2018). "For instance, downregulation of OGT protein levels under pharmacological inhibition of OGA has been demonstrated in a range of cell lines including those of cervical cancer, neuroblastoma, leukemia, colon cancer, and fibroblast origins." (PMID 33801653, 2021). "In addition, the transient overexpression of XIAP WT was found to decrease of OGT levels in SW13, SW480, and SW620 colon cancer cell lines." (PMID 32994395, 2020). "We observed that 27 pairs of samples showed higher levels of OGT expression in cancer tissues compared to the matched tissues, indicating that OGT expression positively correlates with PGK1 glycosylation levels in colon cancer." (PMID 31911580, 2020).
colon cancer (continued). "In this study we found that in colon cancer cells the inhibition of OGT or the exposure of cells to an acute nutritional stress mimicking the lack of OGT, induce the appearance of an aggressive CD133/CD44 double positive CSC subpopulation." (PMID 31139149, 2019). "Here we confirmed that OGT is overexpressed in colon cancer cells compared with non-malignant colon cells." (PMID 31139149, 2019). "In 5-fluorouracilresistant colon cancer cells (SNUC5/5-FUR), highly expressed OGT binds to TET1 and recruits to the Nrf2 (nuclear factor erythroid 2-related factor 2) promoter region, suggesting the role of OGT in TET1-mediated Nrf2 expression." (PMID 28488246, 2017). "On the other hand, OGA protein levels quickly decreased after Cre-mediated knockout of OGT in mouse embryonic fibroblasts, but OGA knockdown in colon cancer cells did not significantly decrease OGT protein expression." (PMID 25520704, 2014). "(2010) showed that H630 colon cancer cells resistant to trifluorothymidine (TFT), a fluorinated thymidine analog that is part of TAS-102 chemotherapy and shares the anabolic pathway of TS inhibition with 5-FU, underexpress OGT, Solute Carrier family 29A (SLC29A), and TK." (PMID 36059648, 2022). "Consistent with this, it has been documented that the inhibition of OGT in colon cancer cells or the incubation of cells under acute nutritional stress that mimics the lack of OGT induces the emergence of an aggressive CD133/CD44 double-positive CSC subpopulation." (PMID 33828530, 2021). "Therefore, it could explain that stable XIAP overexpression would have a smaller effect on OGT and total O-GlcNAc levels in MDA-MB231 and A549 cells than in HCT116 colon cancer cells." (PMID 32994395, 2020). "Regarding these recent observations, we wondered whether silencing OGT expression affects biological properties of colon cancer-derived cell lines (HT29 and HCT116) in comparison to a normal colon cell line (CCD841CoN, derived from a fetus)." (PMID 27252680, 2016). "To determine the levels of O-GlcNAcylation, OGT expression, and OGA expression in colon cancer cells compared to non-malignant colon cells, we performed FACS analysis, Western blot analysis, and immunofluorescence assays." (PMID 31139149, 2019).
lung carcinoma (25 papers, 2015 to 2025). "Among the identified candidate O-GlcNAcylated proteins, SAM68 was validated to be O-GlcNAcylated and was shown to be associated with OGT in the nucleus of lung cancer cells." (PMID 35008409, 2022). "We observed enhanced mRNA level of OGT in cases of lung cancer and its positive correlation with both malignancy and metastasis." (PMID 37308732, 2024). "Previous study indicated a notable increase in O‐GlcNAcylation and OGT expression in lung cancer tissues when compared to the corresponding adjacent tissues." (PMID 39358921, 2024). "SRC-associated in mitosis of 68 kDa (SAM68) is O-GlcNAcylated and predominantly interacts with OGT in the nucleus, promoting lung cancer cell migration and invasion." (PMID 39285476, 2024). "In lung cancer, inhibiting OGT has been shown to attenuate HBP-mediated glycosylation and disrupt cancer cell growth and survival." (PMID 37880766, 2023). "In lung cancer, O-GlcNAcylation and expression of OGT are increased, potentially promoting tumorigenesis and cancer progression." (PMID 37256139, 2023). "This study highlights the pivotal role of LSD2 in suppressing lung cancer growth through the regulation of OGT." (PMID 37880766, 2023). "altogether, OGT is typically overexpressed in lung cancer, resulting in hyper-O-GlcNAcylation of tumorigenesis and metastatic-related proteins." (PMID 37256139, 2023). "It has been reported that knockdown of OGT expression in A549 lung cancer cells decreases their invasiveness in vitro." (PMID 35008409, 2022). "In squamous cell lung cancer, O-GlcNAcylation and increased OGT levels were observed in lung cancer cells compared with the adjacent lung tissue." (PMID 34771527, 2021). "In this study, we have demonstrated that the regulatory mechanisms associated with modulating levels of O-GlcNAc-cycling enzymes according to cellular O-GlcNAcylation status appear to be different for OGA and OGT in lung cancer cells." (PMID 33801653, 2021). "On the other hand, our data clearly demonstrated that modulation of OGT expression in response to changes of O-GlcNAcylation is conducted through translation control in lung cancer cells." (PMID 33801653, 2021). "In the present study, inhibition of OGT by miR-7-5p decreased the growth and cancer metabolism of lung cancer." (PMID 33251387, 2020). "In conclusion, miR-7-5p functions as a tumor suppressor by targeting OGT, thus inhibiting glycolysis and metabolism in lung cancer." (PMID 33251387, 2020). "It has been recently reported that LSD2 histone demethylase acts as an E3 ubiquitin ligase and promotes the proteasomal degradation of OGT in A549 lung cancer cells." (PMID 32994395, 2020). "In line with this, reducing intracellular OGT levels has been shown to inhibit the growth of lung cancer cells." (PMID 33194731, 2020). "O-GlcNAcylation and O-GlcNAc transferase (OGT) expression was significantly elevated in lung cancer tissues." (PMID 30619732, 2018). "Lung carcinoma tissues in Su, Okayama and Landi datasets were found to have both high OGT and low MGEA5 levels as compared with normal tissues." (PMID 28878262, 2017). "Additionally, OGT knockdown has been shown to inhibit the expression of EMT markers (N-cadherin and Slug), migration, and invasion in lung cancer cells, with the interaction between OGT and STAT3 playing a crucial role in this process." (PMID 39285476, 2024). "Our study also addresses an unmet clinical need through the combination of OGT inhibition and anti-PD-L1 therapy, which may represent a promising strategy for colorectal and lung cancer therapy." (PMID 38168435, 2024). "In lung cancer cells, OGT also regulates metastasis ability via activating IL-6/STAT3 signaling." (PMID 37838167, 2023). "Thus, targeting OGT holds promise as a therapeutic approach to inhibit HBP-driven oncogenic processes in lung cancer." (PMID 37880766, 2023).
lung carcinoma (continued). "Similarly, increased O-GlcNAcylation by IL-8 stimulation in colon and lung cancer cells results in increased cancer stem-like cell populations, which can be inhibited by treatment with an OGT inhibitor." (PMID 37838167, 2023). "OGT has potential as a biomarker and drug target for lung cancer." (PMID 37256139, 2023). "Increasing OGT-meditated O-GlcNAcylation levels could affect the occurrence and progression of cancers, including lung cancer." (PMID 35356257, 2022). "While the O-GlcNAcylation status of LSD2 remains unknown, the interaction of LSD2 and OGT displayed an anti-growth effect in lung cancer A549 cells by reducing the stability and protein level of OGT." (PMID 36291918, 2022). "In the present study, inhibition of OGT by miRNA decreased lung cancer metabolism." (PMID 33251387, 2020). "Interestingly, A549 lung cancer cells increase glucose uptake, O-GlcNAc status, and OGT expression during EMT induced by TGF-β47, so we assumed that there would be a new O-GlcNAc-modified protein delivering TGF-β signals." (PMID 33199824, 2020). "SMAD4 protein levels were checked by treating A549 lung cancer cells with inhibitors of O-GlcNAc editing enzymes which caused thiamet-G, an OGA inhibitor, to increase SMAD4 levels whereas SMAD4 levels decreased when treated with OSMI-1, an OGT inhibitor." (PMID 33199824, 2020). "In this study, we observed substantial OGT suppression by miR-7-5p in lung cancer cell lines." (PMID 33251387, 2020). "Given the increasing importance of immunotherapy for the management of patients with that OGT inhibitors, combined with anti-PD-L1 blockade may offer a particularly attractive strategy for the treatment of colorectal and lung cancer, which are instrumental in turning ‘cold tumors’ into ‘hot tumors’." (PMID 38168435, 2024). "Thus, reducing PRPS1 activity by silencing OGT could resensitize lung cancer cells to chemoradiotherapy." (PMID 37308732, 2024). "Thus, the increased G6PD glycosylation correlates with the increased OGT expression in lung cancer." (PMID 26399441, 2015). "T454-phosphorylated OGT has recently been reported to bind robustly with the transcription factor NRF2 and promote lung cancer malignancy." (PMID 41005476, 2025). "Our findings indicate that OGT O‐GlcNAcylates NRF2 at Ser103, and this modification plays a role in cellular antioxidant, lung cancer malignancy, and cisplatin resistance." (PMID 39358921, 2024). "We also measured OGT and PRPS1 O-GlcNAcylation levels in fresh frozen samples of lung cancer tissues obtained during surgery." (PMID 37308732, 2024). "OGT directly modifies STAT3, which enhances phosphorylation of STAT3 to promote metastasis in lung cancer." (PMID 37838167, 2023). "While OGT-mediated O-GlcNAcylation promoted STAT3 phosphorylation and transcriptional activity in lung cancer." (PMID 38008713, 2023). "To investigate the existence of feedback loops for the maintenance of cellular O-GlcNAc homeostasis in lung cancer cells, we examined the expression of OGA and OGT under conditions with varying extents of cellular O-GlcNAcylation." (PMID 33801653, 2021). "In this study, we investigated the O-GlcNAc-feedback regulation of OGT and OGA expression in lung cancer cells." (PMID 33801653, 2021). "In non–small cell lung cancer (NSCLC) cells, glucose promotes the arginine methylation of OGT." (PMID 41005476, 2025). "OGT and O-GlcNAcylation may play a key role in the IL-6/STAT3 signaling-induced migration and invasion of lung cancer." (PMID 37256139, 2023). "High levels of OGT and SAM68 result in poor prognosis of LUAD, and O-GlcNAcylated SAM68 may participate in modulating lung cancer aggressiveness." (PMID 37256139, 2023). "It remains to be determined whether this control mechanism of OGT and OGA expression is also employed by lung cancer cells." (PMID 33801653, 2021).
lung carcinoma (continued). "Similarly, reductions in OGT levels have shown to inhibit growth of lung cancer cells; however, the role of OGT inhibitor in cancers have not been elucidated using an investigational agent." (PMID 34771527, 2021). "We suggest that OGT is regulated through the control of translational efficiency by 4E-BP1, while the expression of OGA could involve epigenetic mechanisms in transcriptional control in lung cancer cells." (PMID 33801653, 2021). "Additionally, we analyzed the mRNA expression of OGT and MGEA5 (encoded OGA) using OncomineTM bioinformatics database and found a remarkable increase in the OGT and/or a decrease in the MGEA5 in lung carcinoma tissues compared with normal lung tissues in many datasets." (PMID 28878262, 2017). "OGT has also been reported to impel the mobility and invasion of NSCLC cells by regulating O-GlcNacylation, demonstrating its important role in lung cancer; however, there is still a lack of research on SCLC." (PMID 35356257, 2022). "However, inhibition of OGT and OGA by altering O-GlcNAc levels did not result in an increased sensitivity of cisplatin in lung cancer cells." (PMID 34771527, 2021).
Obesity (25 papers, 2017 to 2025). Accumulation of substantial excess body fat. "Selectively OGT deletion in the αCaMKII cells of the PVN caused obesity and hyperphagia, as well as increased fat mass and liver weight gain." (PMID 35527999, 2022). "Deletion of OGT in α-CaMKII-positive periventricular nucleus (PVN) neurons in the hypothalamus has been previously shown to cause obesity in part due to hyperphagia." (PMID 33460647, 2021). "Relevant to the obesity phenotype, it is unlikely, however, that loss of OGT in the intestine contributed as deletion of OGT in intestine epithelial cells causes weight loss in mice." (PMID 33460647, 2021). "Ablation of OGT in AgRP neurons causes white adipose tissue browning and confers protection from diet-induced obesity." (PMID 33460647, 2021). "We observed that mHFD feeding rescued the obesity-associated phenotype of OGT FKO mice, including the body weight, fat mass, energy intake, and contents of palmitate (C16:0) and oleate (C18:1) in DAG." (PMID 30504766, 2018). "They observed that OGT knockout results in decreased O-GlcNAcylation and increased PLN1 phosphorylation in visceral adipose tissue, which promotes lipolysis and rapid weight loss, whereas OGT overexpression in mouse visceral adipose tissue inhibits lipolysis and favors diet-induced obesity." (PMID 36058931, 2022). "To investigate whether the deletion of OGT and IL-15rα could negates the mKO protection against metabolic perturbations associated with obesity, we fed mice with a HFD." (PMID 34326778, 2021). "Altogether, our results reveal that OGT is a risk factor for obesity and the elevation of O-GlcNAcylation in adipose tissue may serve as a critical link between nutrient surplus and whole-body metabolic dysfunction." (PMID 31924761, 2020). "To clarify whether adipocyte OGT was associated with hematopoietic abnormalities in obesity, we first conducted a peripheral CBC analysis, and found that WBC count was significantly reduced in the HFD-OGT-AKO group compared to the HFD-WT group, with no statistical change observed in RBC or PLT." (PMID 40389445, 2025). "As the development of OGT inhibitors is progressing rapidly, systematically inhibiting OGT presents a promising strategy to combat obesity-induced hematologic malignancies." (PMID 40389445, 2025). "Loss of adipocyte OGT decreases serum NEFA levels, reduces white adipose tissue, and inhibits HSC differentiation into monocytes in HFD-induced obesity." (PMID 40389445, 2025). "Here, we elucidate the molecular mechanisms by which adipocyte OGT promotes the differentiation of HSCs into monocytes in obesity, regulating monocyte formation through the OGT-NEFA-CD36/FABP4 pathway." (PMID 40389445, 2025). "To further explore the role of adipocyte-expressed OGT in obesity, we applied adipocyte-specific OGT knockout (OGT-AKO) mice along with wild-type (WT) mice." (PMID 40389445, 2025). "Together, these results indicate that adipocyte OGT contributes to the increased monocytes in HFD-induced obesity." (PMID 40389445, 2025). "Adipocyte OGT is crucial for monocyte development in high-fat diet (HFD)-induced obesity, promoting an increase in peripheral blood monocytes through transcriptional activation of nonesterified fatty acids (NEFA), a critical energy substrate." (PMID 40389445, 2025). "In islets from patients who are lean or have obesity, we analyzed the baseline protein levels of OGT and mTORC1, along with their activity." (PMID 39388284, 2024). "We show reduced OGT and mTORC1 activity in islets of a preclinical β cell dysfunction model and islets from humans with obesity." (PMID 39388284, 2024). "The reduced impact of the OGT inhibition in hyperglycemic settings is a potential impact on obesity/OGT inhibitor effectiveness that will bear further examination." (PMID 37231419, 2023). "To test the impact of a hyperglycemic tumor microenvironments on OGT, we used B6.Rag1 knockout mice, an obesity-compatible mouse model, to measure effects in TNBC tumors." (PMID 37231419, 2023).